NHLRC4 (NHL repeat containing 4)
Tractability: No criterion of Open Targets' tractability assessment is met for any kind of drug.
Gene: Protein-coding gene on chromosome 16 (567,005 to 569,495, forward strand). Ensembl gene ENSG00000257108.
Subcellular location (Human Protein Atlas): Mitochondria
Gene Ontology:
Molecular function: protein binding
Genetic constraint (gnomAD): Loss-of-function variants: 0 observed, 0.58 expected, observed/expected ratio (o/e) 0, 90% interval 0 to 1.82. That is too few expected variants to judge how well the gene tolerates losing a copy. Missense variants: 158 observed, 155.21 expected, observed/expected ratio (o/e) 1.02, 90% interval 0.89 to 1.16. Synonymous variants: 73 observed, 70.15 expected, observed/expected ratio (o/e) 1.04, 90% interval 0.86 to 1.26.
Homologues: Orthologues: chimpanzee NHLRC4 (99% identical), mouse Nhlrc4 (79% identical), guinea pig NHLRC4 (77% identical), dog NHLRC4 (71% identical), tropical clawed frog nhlrc4 (52% identical). Paralogues in human: PRR35 (16% identical), ZNF750 (15% identical).
Diseases named in the same sentence as NHLRC4 in open-access papers:
NHLRC4 is named in the same sentence as 3 diseases in open-access papers, as found by Europe PMC text mining. Sharing a sentence is not in itself a finding about the gene and the disease. The quoted sentences say what the papers report.
tumor (2 papers, 2021 to 2023). "Some genes, such as the NHLRC4 gene (ubiquitin protein ligase activity) showed differential methylation (hypomethylation) in tumor tissue that was greater in the presence of BRAF mutation compared to wild-type patients." (PMID 36975440, 2023).
NHLRC4 also shares sentences with these, for which no sentence is quoted: breast carcinoma (1 paper); insomnia (1).